LINC00862 (long independently transcribed non-coding RNA 862)
Synonyms: C1orf98; SMIM16
Gene: Long non-coding RNA gene on chromosome 1 (200,241,638 to 200,400,710, reverse strand). Ensembl gene ENSG00000203721.
Subcellular location: Membrane
Diseases named in the same sentence as LINC00862 in open-access papers:
LINC00862 is named in the same sentence as 3 diseases in open-access papers, as found by Europe PMC text mining. Sharing a sentence is not in itself a finding about the gene and the disease. The quoted sentences say what the papers report.
hepatoma (1 paper, 2026). "Our data revealed a significant up-regulation of LINC00862 by RBM47 in hepatoma cells." (PMID 41487470, 2026). "To validate the correlation between in vitro expression of LINC00862 and RBM47, we employed qRT-PCR to assess the expression levels of RBM47 mRNA across 5 hepatoma cell lines." (PMID 41487470, 2026).
tumor (2 papers, 2024 to 2026). "This suggests that LINC00862 is potentially involved in tumor regulation and may be associated with molecules that exhibit protein-binding functions." (PMID 41487470, 2026). "CTD-2066L21.3, LINC00355, CTD-2555C10.3, OGFRP1, and LINC00862 were found to be substantially expressed in tumor cells but expressed at low levels in normal cells." (PMID 38710798, 2024).
LINC00862 also shares sentences with these, for which no sentence is quoted: cancer (1 paper).